MYOG (myogenin)
Diseases named in the same sentence as MYOG in open-access papers (continued):
Sharing a sentence is not in itself a finding about the gene and the disease.
Esotropia (2 papers, 2021 to 2023). A form of strabismus with one or both eyes turned inward ('crossed') to a relatively severe degree, usually defined as 10 diopters or more. "The expression level of MYOG has been found to be increased in the paralytic lateral rectus muscle compared with those with concomitant esotropia (controls)." (PMID 38173464, 2023). "The results of RT-PCR revealed that PAX7, MYOG, PITX1, SIX1 and SIX4 showed higher levels of expression, while that of MYOD a lower level of expression within the paralytic esotropia group as compared with that in the control group (p < 0.05)." (PMID 34044792, 2021). "Such a mechanism would explain the low expression of MYOD in the lateral rectus muscle of the paralytic esotropia group, while SIX1, PAX7 and MYOG are up-regulated." (PMID 34044792, 2021).
heart failure (2 papers, 2015 to 2023). Inability of the heart to pump blood at an adequate rate to meet tissue metabolic requirements. "In cell culture, myogenin expression is suppressed in differentiating myocytes treated with tumor necrosis factor-α (TNF-α), a cytokine that commonly increases during heart failure." (PMID 26452256, 2015). "The mechanisms involved in myogenin reduction during heart failure are not completely understood." (PMID 26452256, 2015).
hyperphosphatemia (2 papers, 2022 to 2024). Abnormally high level of phosphate in the blood. "Indeed, our data show that the exposure of C2C12 cells to a condition of extracellular hypocalcemia associated with hyperphosphatemia induced a decrease of MyoD and myogenin even after 1 day of differentiation." (PMID 37819413, 2024).
medulloblastoma (2 papers, 2019 to 2023). A malignant, invasive embryonal neoplasm arising from the cerebellum. "Prior studies show that WT P7 cerebella and SHH medulloblastomas contain populations of cells that express MYOD1 without inducing MYOG or activating a myogenic program." (PMID 36635771, 2023).
muscular dystrophies (2 papers, 2022 to 2025). "Therefore, delayed activation of MYOG might be a common feature of muscular dystrophies associated with NE proteins and might be caused by altered epigenetic regulation." (PMID 36362402, 2022). "Inhibiting myostatin and muscular dystrophy factors such as atrophin-1 and MuRF-1 and enhancing myogenic factors including MyoG (‌myogenin) and MyoD (myoblast determination) can improve muscle atrophy." (PMID 40407708, 2025).
Myoepithelial carcinoma (2 papers, 2020 to 2022). "Myoepithelial carcinoma expresses cytokeratin and myogenic markers, such as myogenin, smooth muscle actin and HHF35." (PMID 34996495, 2022).
soft tissue neoplasm (2 papers, 2014 to 2025). A benign, intermediate, or malignant neoplasm that arises from the soft tissue. "Other markers, such CD34, CD117, myogenin, and DOG1 (discovered on GIST, also known as anoctamin 1), have also been proposed to play a significant role in identifying soft tissue tumors." (PMID 41262926, 2025).
spindle cell rhabdomyosarcoma (2 papers, 2021 to 2022). An uncommon variant of rhabdomyosarcoma characterized by the presence of whorls of spindle cells forming a storiform pattern. "Immunohistochemical analysis showed negative staining with Cytokeratin, S100, CD34, Stat6, h-Caldesmon and EMA while the tumour cells were positive for desmin, myogenin, smooth muscle actin, CD-99 and MyoD1 thus confirming the diagnosis of spindle cell rhabdomyosarcoma." (PMID 34104191, 2021). "Positivity for epithelial antibody markers and negative staining for skeletal muscle-specific markers, namely desmin, myogenin and MyoD1, ruled out a spindle cell rhabdomyosarcoma." (PMID 34514569, 2022).
spindle cell tumor (2 papers, 2011 to 2013). "Histologically, it is described as a highly cellular spindle cell tumor with frequent mitotic activity, staining positive for desmin, myosin, myoglobin, myogenin, and myoD1 markers." (PMID 23936713, 2013). "Histopathology of RMS mainly presented as embryonic (ERMS) or spindle-cell tumors, which expressed myogenic factors to various degrees, such as myogenin, Myf5, or desmin (not shown)." (PMID 21533183, 2011).
Wilms tumor (2 papers, 2011 to 2025). An embryonal neoplasm characterized by the presence of epithelial, mesenchymal, and blastema components. "EDNRA is directly activated by downstream targets of the WNT/beta-catenin pathway in Wilms tumors, and WNT/beta-catenin pathway could regulates the function of MyoD and myogenin in myogenesis." (PMID 21637832, 2011).
Achalasia (1 paper, 2024). A disorder of esophageal motility characterized by the inability of the lower esophageal sphincter to relax during swallowing and by inadequate or lacking peristalsis in the lower half of the body of the esophagus. "Additionally, biopsy and immunohistochemistry for markers like desmin and myogenin, which are specific to RMS, are crucial in differentiating ERMS from benign esophageal strictures or achalasia." (PMID 39703342, 2024).
angiosarcoma (1 paper, 2013). A malignant tumor arising from the endothelial cells of the blood vessels. "From its hyalinizing pseudovascular appearance and sometimes focal and dot-like desmin and myogenin expression, these tumors could easily be mistaken for variants of angiosarcoma, extraskeletal myxoid chondrosarcoma, osteosarcoma, or sclerosing epithelioid fibrosarcoma." (PMID 23766666, 2013).
bladder cancer (1 paper, 2006). "Identification of myogenin expression in bladder cancer cell lines is novel, and further research will be needed to determine if this transcription factor is actually active." (PMID 16412233, 2006).
cardiac hypertrophy (1 paper, 2016). "Since the NFAT-calcineurin pathway is an important mechanism that promotes cardiac hypertrophy during torpor, the upregulation of MyoG by NFAT during LT may act as a feedback mechanism in squirrel cardiac muscle to inhibit hypertrophy-promoting pathways." (PMID 27602284, 2016).
chronic kidney disease (1 paper, 2024). Impairment of the renal function secondary to chronic kidney damage persisting for three or more months. "Formononetin showed anti-muscle atrophic effects in chronic kidney disease mice and myogenic effects via regulation of MyoD and myogenin in C2C12 myotubes." (PMID 38966418, 2024).
cutaneous melanoma (1 paper, 2025). A primary melanoma arising from atypical melanocytes in the skin. "Case presentation: In this respect, we present two cases of primary cutaneous melanomas exhibiting rhabdoid features and genuine divergent rhabdomyosarcomatous differentiation confirmed by immunoreactivity for myogenin and loss of positivity for some melanocytic markers." (PMID 40506928, 2025).
dysferlinopathy (1 paper, 2020). "In conclusion, we did not observe a significant increase of dysferlin or myogenin in myotubes from a dysferlinopathy patient when treated with EB1089, oprozomib and ixazomib." (PMID 33246442, 2020). "Treatment with oprozomib, ixazomib and EB1089 in myotubes from a dysferlinopathy patient promoted a trend towards increased expression of dysferlin and myogenin, but this low increase did not translate into higher sarcolemmal repair neither higher fusion index than that in untreated myotubes." (PMID 33246442, 2020).
emphysema (1 paper, 2019). "Salidroside treatment decreased emphysema, significantly ameliorated lung function, increased antioxidant, but reduced MDA, IL-6 and TNF-α levels in serum and GN tissues of rats, accompanied by decreased myostain, but increased myogenin expression in GN tissues." (PMID 31702007, 2019).
epithelioid sarcoma (1 paper, 2023). An aggressive malignant neoplasm of uncertain differentiation, characterized by the presence of epithelioid cells forming nodular patterns. "Epithelioid sarcoma can show rhabdoid and spindle morphology with tumor necrosis, they generally express epithelial markers and CD34, and loss SMARCB1/INII1 expression and don’t express Myo-D1 and Myogenin." (PMID 36998041, 2023).
glioma (1 paper, 2011). A benign or malignant brain and spinal cord tumor that arises from glial cells (astrocytes, oligodendrocytes, ependymal cells). "T protein, which is required for mesoderm formations, is significantly expressed in glioma tissue together with the muscle determination factor Myogenin." (PMID 21483788, 2011).
lung carcinoma (1 paper, 2020). "Nonetheless, myogenin was found increased also in human cachectic muscle from patients with lung cancer (where also an increased NF-Kb/PAX7 signaling occurred as in our samples)." (PMID 32824440, 2020).
metastatic tumors (1 paper, 2015). "We showed that percentage of both c-Myb and myogenin positive cells was reduced in localized tumors compared to metastatic tumors." (PMID 26462877, 2015).
muscular disease (1 paper, 2022). Myopathy is a peripheral nervous system disease consisting of any abnormal condition or disease of the muscular tissues; commonly designates a disorder involving skeletal muscle. "In addition, ceramide inhibits myogenin synthesis and myotube formation, and several studies have identified the relationship between ceramide and various muscular diseases." (PMID 35563168, 2022).
Myoclonus (1 paper, 2020). Very brief, involuntary random muscular contractions occurring at rest, in response to sensory stimuli, or accompanying voluntary movements. "In the period after the 20th stimulus (POST, 3rd cell), there was the presence of the same limbic behaviors, when compared with the 1st stimulus (3rd cell), such as EB, MT, MYOh, MYO1, SAL, and REAR, plus Generalized Myoclonus (MYOg) and Falling (FALL)." (PMID 33250852, 2020).
myotonic dystrophy type 1 (1 paper, 2021). Steinert disease, also known as myotonic dystrophy type 1, is a muscle disease characterized by myotonia and by multiorgan damage that combines various degrees of muscle weakness, arrhythmia and/or cardiac conduction disorders, cataract, endocrine damage, sleep disorders and baldness. "Interestingly, KCa1.1 expression in myotonic dystrophy type 1 (DM1) myoblasts was found to be significantly decreased, whereas introducing functional KCa1.1 α-subunits into DM1 myoblasts reduced their proliferation to normal levels and rescued the expressions of MEF2 and myogenin." (PMID 34948411, 2021).
Pancytopenia (1 paper, 2020). An abnormal reduction in numbers of all blood cell types (red blood cells, white blood cells, and platelets). "A 7-year-old boy presenting with severe pancytopenia was diagnosed with metastatic RMS after bilateral bone marrow aspiration and biopsy (BMAB) revealed infiltration with alveolar-pattern RMS cells, which were immunoreactive to desmin and myogenin." (PMID 32669548, 2020).
renal cell carcinoma (1 paper, 2007). "The renal neoplastic cells failed to stain with antibodies against renal cell carcinoma marker (RCC) {Ventana}, S-100 protein (Ventana), chromogranin (Ventana), cytokeratins (AE1/AE3, 8/18, 7/20) {Ventana}, CD34 (Ventana), and myogenin (Ventana) {not shown}." (PMID 18053181, 2007).
rotator cuff tears (1 paper, 2018). "To date, only a few genes, such as those coding for peroxisome proliferator-activated receptors gamma (PPARγ), CCAAT-enhancer-binding proteins alpha (CEBPα), myogenin, myostatin, and matrix metallopeptidases (MMPs), have been identified in relation to muscle changes after rotator cuff tears." (PMID 30671462, 2018).
small cell carcinoma of the bladder (1 paper, 2011). "In this study, we compared the expression of cytokeratin, myogenin, synaptophysin and chromogranin in rhabdomyosarcomatous tumor and small cell carcinoma of the bladder." (PMID 21762516, 2011).
teratoma (1 paper, 2020). A non-seminomatous germ cell tumor characterized by the presence of various tissues which correspond to the different germinal layers (endoderm, mesoderm, and ectoderm). "Pax3 level was slightly higher and Myogenin level was slightly lower in Pax7−/− teratomas than in Pax7+/+ teratomas." (PMID 32552916, 2020).
ZIKV infection (1 paper, 2021). "In agreement with this, the expression of the differentiation regulatory factor MyoG was also inhibited by ZIKV infection despite the occurrence of muscle damage in mice." (PMID 34468171, 2021). "Levels of the differentiation inductor factor MyoG were also reduced following ZIKV infection." (PMID 34468171, 2021).
tumor (166 papers, 1991 to 2026). "Immunohistochemistry: the tumor cells expressed Myogenin (11/13), Desmin (13/13), MyoD1 (12/13) and Myoglobin (5/9)." (PMID 40161378, 2025). "Immunohistochemical staining revealed positive expression of Myogenin, MyoD1 and Desmin in the tumor cells." (PMID 40520793, 2025). "Immunohistochemically, the tumor cells are positive for desmin and exhibit heterogeneous nuclear staining for myogenin and MYOD1." (PMID 40282503, 2025). "Subsequent pathological examination revealed tumor cells with positive immunoreactivity for desmin, myogenin (MyoG), and MyoD1, with a Ki-67 proliferation index that exceeded 60%." (PMID 40630199, 2025). "The results revealed the presence of desmin (DES) in the majority of tumor cells and the focal expression of myogenin (MYOG) and MYOD1." (PMID 41373578, 2025). "The tumor cells in this case diffusely expressed Desmin, Myogenin, and MyoD1, which can lead to the diagnosis of ARMS." (PMID 38835374, 2024). "Overall, the single-cell expression in PDX-derived RMS primary cultures showed a specific expression density of the DiPRO1 gene in cycling cells, mesenchymal MuSC, and MYOG-expressing differentiated tumor cell subpopulations." (PMID 39009887, 2024). "Immunophenotyping tests showed positivity of tumor cells for Desmin, Myogenin, MyoD1, Syna, CD56, and ALK." (PMID 38835374, 2024). "Immunohistochemistry showed positive staining for cell CyclinD1, CD10, Caldesmon, and Vimentin in the tumor cells, with some tumor cells also demonstrating positive labeling for MyoD1, CKpan, and Myogenin." (PMID 39009979, 2024). "Immunohistochemistry reveals tumor cells’ reactivity to vimentin, desmin, actin, myoglobin, MyoD1, and myogenin." (PMID 36777814, 2023). "One MCP tumor used for the analysis was distinct from the others and expressed lower levels of Myogenin and MyoD1, prompting us to investigate the heterogeneity present between MCP tumors." (PMID 37968277, 2023). "Immunohistochemically, apart from desmin and focal SMA immunoreactivity, tumor cells also displayed multifocal myoD1 and focal myogenin positivity." (PMID 35642345, 2023). "With this approach, tumor subpopulation and heterogeneity were labeled based on the activation of different promoters (myf5, myogenin-H2B, and mylpfa) at different stages in the muscle development." (PMID 37958442, 2023). "In contrast, myogenic differentiation was strikingly increased as seen from MHC and MYOG levels by IHC and western blot analysis of tumour lysates." (PMID 35490194, 2022). "Using this modified MYOG promoter to drive expression of the HSV-TK suicide gene resulted in specific targeting of tumour cells both in vitro and in vivo." (PMID 36158201, 2022). "Microscopically, numerous histiocytes and foamy cells covered the actual tumor cells that were positive for desmin, MyoD1, and myogenin, suggesting striated skeletal muscle cell differentiation." (PMID 34128847, 2021). "The MYOD1 plays a crucial role in accelerating the transcription of p21 (a cyclin dependent kinase that acts as a tumor suppressor) and myogenin to remove the cells from cell cycle and terminate multiplication of differentiated myocytes." (PMID 34722422, 2021). "Immunohistochemically(IHC) analysis revealed that the tumour cells were positive for Desmin, Vimentin, Myo-D1 and Myogenin." (PMID 34670517, 2021). "The characterization of this cell line has further contributed to define the characteristics of the rare group of SRF-NCOA2 neoplasms and their rhabdomyoblastic nature, clearly demonstrated by MYOD1 and myogenin expression by tumor cells." (PMID 34067464, 2021). "Developmentally, RMS is believed to originate from myogenic progenitors, a concept supported by the expression of myogenic genes such as desmin and myogenin in RMS tumor cells." (PMID 33846547, 2021). "The staining of RMS tumor cells with Myogenin and MyoD1 revealed that B7-H3 is expressed by tumor cells and not detected in the stroma or tumor-infiltrating immune cells." (PMID 34572755, 2021).